IL15RA (interleukin 15 receptor subunit alpha)
Diseases named in the same sentence as IL15RA in open-access papers (continued):
Sharing a sentence is not in itself a finding about the gene and the disease.
Ureteral obstruction (1 paper, 2021). Obstruction of the flow of urine through the ureter. "We first compared IL-15 and IL-15Rα mRNA expression in obstructed kidneys (UUO-kidneys) and contralateral non-obstructed kidneys (CTL-kidneys) on day-8 post-ureteral obstruction." (PMID 34769128, 2021). "Since endogenous IL-15 expression decreased in nephrectomized human allografts evolving toward fibrosis and kidneys in the unilateral ureteral obstruction (UUO) model, we explored IL-15’s renoprotective role by pharmologically delivering IL-15 coupled or not with its soluble receptor IL-15Rα." (PMID 34769128, 2021).
uveitis (1 paper, 2022). An inflammatory process affecting a part of or the entire uvea. "However, a variety of the highest-scoring interactions involved ICAM1 and IL15RA, indicating that they may be immune-mediated causes of uveitis." (PMID 36163311, 2022). "We selected the chemokine/chemokine receptor genes IL10 receptor (IL10R), IL15, IL15 receptor α (IL15RA) and the adhesion gene ICAM1 that were believed to be the common biomarkers of many forms of uveitis." (PMID 36163311, 2022).
tumor (115 papers, 2009 to 2026). "We generated trifunctional antibody-cytokine fusion proteins composed of a scFv antibody directed against the fibroblast activation protein (FAP) as a tumor associated model antigen, IL-15 fused to an IL-15Rα fragment (RD), and either IL-7 or IL-21." (PMID 40370435, 2025). "Upon engagement of tumor cells by exogenous IL-15, we detected the association of IL-15Rα with the IL-2/IL-15Rβ and IL-2Rγ chains." (PMID 38637902, 2024). "We also found that tumor cell IL-15Rα was associated with IL-15β and IL-15Rγ upon engaging with extracellular IL-15." (PMID 38637902, 2024). "The applied chemoimmunotherapy caused the highest inhibition of tumor growth in the group receiving DC/IL-15/IL-15Rα/TAg + DC/IL-18/TAg at the level of 72.4%." (PMID 37545526, 2023). "The biNV-IL-15 treatment not only inhibited the tumor growth but also prevented lung and liver metastasis of the tumor in contrast to IL-15:IL-15Rα and IL-15:IL-15Rα+biNV, causing an extended survival time." (PMID 37875481, 2023). "IL-15, a type I cytokine together with IL-2, IL-4, IL-7, IL-9, and IL-21, promotes survival of T, B, and NK cells by binding to IL-15α, encoded by IL15RA, negatively regulating both carcinogenesis and tumor growth." (PMID 36432658, 2022). "While IL-15 alone has a short half-life, administration of IL-15 linked to soluble IL-15Rα significantly increases its half-life, leading to improved in vivo tumor response through increased survival of memory T and NK cells." (PMID 33410096, 2021). "Expression levels of DLK2 and IL15RA were also aligned across survival risk groups with IL15RA being relevant given its evolving role in targeted therapies to overcome resistance and improve anti-tumor effect." (PMID 39123468, 2024). "Indeed, recombinant human IL-15 and sIL-15/IL-15Rα, employed alone or in association with other therapies, cause efficient tumor regession in several experimental tumor models." (PMID 37334356, 2023). "The biomimetic nanovaccine is composed of cytomembrane vesicles, derived from genetically engineered dendritic cells (DC), onto which IL-15/IL-15 receptor α (IL-15Rα), tumor-associated antigenic (TAA) peptide/MHC-I, and relevant costimulatory molecules are simultaneously anchored." (PMID 37875481, 2023). "One of the reasons for curtailed maximum expansion in patient-derived γδT cells could be the dull responsiveness of IL-15Rα to IL-15 resulting from the long-term deficiency in IL-15 within the tumor microenvironment." (PMID 35351861, 2022). "In a previous study, we showed that the therapy targeting experimentally induced lung melanoma in mice with IL-15-encoding MYXV construct (vMyx-IL15Rα-tdTr) delivered by MSCs was effective and was able to reduce the tumor burden as well as triggering the inflow of CD8+ cells." (PMID 33808692, 2021). "The tumor microenvironment can also be modulated by cytokines and/or cellular vaccines such as modified dendritic cells that overproduce IL-12, IL-15/IL-15Rα, and IL-18." (PMID 41846923, 2026). "IFN-I signaling in cDCs, including that induced by STING agonists, upregulates the expression of IL-15/IL-15Rα by cDCs, which is thought to augment anti-tumor immunity via the activation of cDCs, CD8+ T cells, and natural killer (NK) cells." (PMID 40227734, 2025). "At low dose of 3 mg kg-1, four out of six mice treated with Pembrolizumab-IL-15Rα-IL-15 were free of tumor development, while tumor sizes of the other two mice were much smaller than that of control." (PMID 39808627, 2025). "Co-administration of B7-H6M4-LC21 with IL-15/IL-15Rα sushi fusion achieved synergistic tumor inhibition, outperforming T cell-based strategies and emphasizing NK cells’ unique capacity to overcome stromal immunosuppression." (PMID 40873574, 2025). "Their study revealed that fourth generation CAR.19-IL15/IL15Rα had improved proliferation and effectiveness compared with other NK-92 cell-based tumor therapies." (PMID 40519903, 2025).
tumor (continued). "To characterize the distribution of IL-15 complexes and anti-PD-1 mAb in situ and track the interactions with immune cells within the tumor, we fluorescently labeled IL-15Rα-Fc with Cy5 and anti-PD-1 mAb with Cy3." (PMID 41373645, 2025). "To address this gap, we developed a modular immunotherapy platform combining B7-H6-specific BsAbs with a tumor-anchored IL-15/IL-15Rα sushi fusion protein." (PMID 40873574, 2025). "The B7-H6M18/IL-15/IL-15Rα sushi fusion protein enables tumor-localized cytokine activation while preserving effector cell specificity." (PMID 40873574, 2025). "B7-H6M4LC21 exhibited enhanced tumor-killing efficacy (IC50: 5 ng/mL) compared to B7H6M4-OKT3(IC50: 1 ng/mL) when combined with an IL-15/IL-15Ra sushi fusion protein, which augmented NK cell proliferation and cytotoxicity." (PMID 40873574, 2025). "At the same time, IL-15/IL-15Rα complex-secreting NKG2D-CAR T also showed superior anti-tumor activity and survival in vivo." (PMID 40625735, 2025). "Administering IL-15 fused with IL-15Rα (IL-15/IL-15Rα) directly into tumors boosts tumor cell destruction and expands NK and CD8+ T cells." (PMID 40636453, 2025). "Upon intravenous (IV) dosing to tumor-bearing mice, ACTM-838 distributed and enriched in the TME, exhibited specific uptake in tumor-resident phagocytic cells and led to expression of human IL-15/IL15Rα and murine IFNα in the tumor." (PMID 41048107, 2025). "When IL-15/IL-15Rα is combined with a PD-L1-specific antibody (K2-Fc), it further enhances tumor cell killing by boosting NK-cell activation independently of T cells." (PMID 40636453, 2025). "The IL-15/IL-15Rα complex secreted from virus-infected tumor cells not only facilitates the recruitment of CAR-NK cells to the tumor site, but also promotes NK cell survival and priming." (PMID 39066359, 2024). "IL-15 functions as an upstream regulator of tumor-infiltrating CD8+ T cells, and the IL-15/IL-15Rα+ axis plays a crucial role in anti-tumor immunity." (PMID 39055561, 2024). "However, when exogenous IL-15 engaged tumor cells, a complex containing the IL-15Rα, IL-2/IL-15Rβ, and IL-2Rγ chains was formed, indicating that the differential actions of intracellular and extracellular IL-15 on tumor cells might be caused by their distinctive modes of IL-15 receptor engagement." (PMID 38637902, 2024). "Our data showed that exogenous IL-15, but not the IL-15-IL-15Rα complex inhibited cell migration, suggesting that the action of exogenous IL-15 requires the presence of tumor cell IL-15Rα and cis-presentation." (PMID 38637902, 2024). "Mechanistic analysis revealed that both the intracellular and extracellular IL-15-mediated effects required the expression of IL-15Rα by tumor cells." (PMID 38637902, 2024). "It appears that intratumoral production and/or circulating sIL-15/IL-15Rα complexes contribute to developing a tumor microenvironment favorable for tumor progression and immune escape." (PMID 39199571, 2024). "BiNV-IL-15 obviously improved the percentage of tumor-infiltrating CD8+ T cells and downregulated the level of immunosuppressive Tregs in tumor, implying remarkable advantages over IL-15:IL-15Rα and IL-15:IL-15Rα+biNV." (PMID 37875481, 2023). "We observed that immune cell-mediated tumor cell killing was facilitated when IL-15/IL-15Rα was produced by 624-MEL-GFP cells." (PMID 37923822, 2023). "The resulting tumor spheroids were co-cultured with PBLs, showing tumor cell killing when IL-15/IL-15Rα was produced by the tumor cells." (PMID 37923822, 2023). "In contrast, NK-92-CAR.19-IL15/IL-15Rα cells resulted in tumor growth control for the entire 29 days." (PMID 37818365, 2023). "The PD-1/PD-L1-inhibitor combined with the IL-15/IL-15Rα-nanovesicle complex significantly enhanced the anti-tumor responses." (PMID 37345176, 2023). "When NK cells were depleted, the tumor control was impaired resulting in tumor spheroid growth unless IL-15/IL-15Rα was present in the culture." (PMID 37923822, 2023).
tumor (continued). "CD8+ T cell depletion changed the slope in the IL-15/IL-15Rα condition, resulting in reduced tumor cell killing." (PMID 37923822, 2023). "Delivery of IL-15/IL-15Rα to tumor cells effectively mediated anti-tumor activity and sensitized the tumor microenvironment (TME) for therapy with αPD-L1 therapeutics, mainly by impacting NK cells." (PMID 38250068, 2023). "In a tumor model, IL‐15/IL‐15Rα NVs–PD‐1/PD‐L1 inhibitor 1 treatment effectively delayed tumor growth and further enhanced the antitumor response, inhibited tumor growth, and improved the survival rate of mice." (PMID 37409429, 2023). "We demonstrated that IL-15/IL-15Rα-mediated tumor killing follows distinct kinetics upon CD8+ T cell and NK cell depletion." (PMID 37923822, 2023). "This study demonstrates that gene-based delivery of IL-15/IL-15Rα to tumor cells effectively mediates anti-tumor activity and sensitizes the tumor microenvironment for therapy with αPD-L1 therapeutics mainly by impacting NK cells." (PMID 37923822, 2023). "The biNV-IL-15 displayed the excellent capability of tumor recurrence inhibition in contrast to IL-15:IL-15Rα and IL-15:IL-15Rα+biNV, resulting in superior survival outcomes." (PMID 37875481, 2023). "Membrane-bound IL-15/IL-15Rα (mbIL15) gene has been previously reported to improve the persistence and anti-tumour effect of genetically modified primary T cells in a xenograft animal model." (PMID 36509913, 2023). "This trial was based on the preclinical observation that NK cell activation with artificial IL-15Rα- and 4-1BBL-expressing antigen-presenting cells and soluble IL-15 leads to increased expression of activating receptors and enhanced tumor killing." (PMID 36348457, 2022). "The IL-15RF was constructed by combining IL-15 and IL-15 receptor α (IL-15RA), which together are shown to further improve anti-tumor potency, survival and proliferation in transduced CD8+ T cells compared to IL-15 or IL-15RA alone." (PMID 36348457, 2022). "Vaccination with a BacMam-based IL-15:IL-15Rα cancer vaccine triggered antitumor immune responses in a tumor antigen-specific manner." (PMID 34439192, 2021). "IL-15/IL-15Rα complex has poor stability and can bind to IL-15Rβγ to decrease tumor immune efficacy." (PMID 34386015, 2021). "This suggests that IL-15/IL-15Rα expression had a differential effect on CD8+ T cells recognizing tumor." (PMID 33679747, 2021). "Three days following initial vvDD-IL15/Rα infection, IL-15/IL-15Rα levels rose to a detectable mean concentration of 2,581 pg/ml per 500 mg of tumor tissue by ELISA, while concentrations in tumors of PBS and vvDD treated mice were undetectable." (PMID 33679747, 2021). "Immunization with the BacMam-based IL-15:IL-15Rα cancer vaccine significantly delayed tumor growth by stimulating robust antitumor immune responses in tumor antigen-specific CD8+ T cells and NK cells while simultaneously attenuating Foxp3+ Treg cells." (PMID 34439192, 2021). "Both hetIL-15 and variants of IL-15:IL-15Rα complexes (N-803 and RLI) showed improved pharmacokinetics and anti-tumor activity in animal models and in humans." (PMID 33671252, 2021). "Collectively, the BV-based IL-15:IL-15Rα cell-based cancer vaccine induced potent antitumor responses in both the spleen and the circulatory system through a tumor antigen-specific CD8+ T cell-dependent mechanism." (PMID 34439192, 2021). "In summary, these results indicate that high IL-15/IL-15Rα tumor abundance three days following vvDD-IL15/Rα treatment correlates with a cytotoxic CD8+ T cell immune response." (PMID 33679747, 2021). "sch rhIL-15, hetIL-15, and IL-15:IL-15Rα fusion agonists were also all shown to have anti-cancer activity in several mouse tumor models." (PMID 33671252, 2021). "Using GET to deliver IL-15 and the soluble IL-15Rα on a single plasmid (pAG208), we were able to demonstrate an effective local anti-tumor response similar to that obtained using IL-15 only (pAG170)." (PMID 33096755, 2020).
tumor (continued). "The delivery of IL-15/IL15Rα (pAG208) protected more animals from developing a second tumor than the delivery of IL-15 alone (pAG170) or the delivery of both genes on separate plasmids (pAG115 and pAG170)." (PMID 33096755, 2020). "Our results would predict that shifts in STAT1 splicing towards a predominant expression of Stat1β would considerably compromise NK cell-dependent tumor surveillance and that this defect cannot be overcome by treatment with exogenous IL-15/IL-15Rα." (PMID 33042133, 2020). "Mice that were treated with pIL-15/IL-15Rα complex had a greater level of protection from secondary tumor formation using a lung colonization model." (PMID 33096755, 2020). "Similar results were obtained when IL-15/IL-15rα was substituted for IL-12P70, demonstrating the robustness and transposability of our approach to express proteins of therapeutic interest in a tumor cell-dependent manner." (PMID 31723132, 2019). "IL-15, either in its soluble form (IL-15sol) or complexed with IL-15Rα (IL-15Rc), has been shown to exhibit potent anti-tumor activities in various experimental cancer studies." (PMID 31856922, 2019). "Pre-exposure of NK cells to recombinant IL-15/IL-15Rα further increased the lysis of olaparib treated tumor cells." (PMID 30486888, 2018). "Of these, interleukin‐1β (IL‐1β) showed age‐dependent upregulation in control lungs and tumors from old mice, whereas tumor‐specific upregulation was observed for Ccl7, IL‐15ra, and Cxcr6 cytokines in old mice." (PMID 29047229, 2018). "A trend of increased expression of IL-12β, and IL-15Rα was also observed on tumor-infiltrating CD8+T cells following bortezomib treatment compared to tumor-infiltrating CD8+T cells without bortezomib treatment." (PMID 28052005, 2017). "In this latter model expression of the IL15Rα on cancer cells was needed to efficiently induce granulated NK cells, and expression on host stromal cells was essential to prevent tumor relapse." (PMID 26822794, 2016). "Although IL-15/IL-15Rα EP DC are promising candidates for DC-based vaccination in cancer immunotherapy, the tumor suppressive environment can impede its powerful antitumor effects." (PMID 26675759, 2015). "Blocking IL-15 transpresentation abrogated NK cell-mediated cytotoxicity against tumor cells, pointing to a pivotal role of IL-15 transpresentation by IL-15Rα to exert its NK cell-activating effects." (PMID 26675759, 2015). "Our observations corroborate these findings, including enhanced killing of tumor cells if IL-15 is presented by IL-15Rα, as seen by us using healthy donor and cancer patient material." (PMID 26675759, 2015). "Treatment of tumor-bearing C57BL/6 mice with vMyx-IL15Rα-tdTr resulted in longer survival than similarly treated RAG1-/- mice." (PMID 25329832, 2014). "Similar to the effect observed in RAG1-/- mice, C57BL/6 mice treated with vMyx-IL15Rα-tdTr also had significant intra-tumor infiltration of NK cells, compared to both tdTomato expressing virus and PBS treatment." (PMID 25329832, 2014). "The anti-tumor effect of vMyx-IL15Rα-tdTr in immunocompetent animals showed the same pattern as in RAG1-/- mice, with overall longer median survival in corresponding groups." (PMID 25329832, 2014). "vMyx-IL15Rα-tdTr treatment resulted in tumor stabilization in the majority of animals until day 20, while mice given other treatments were succumbing to tumors at this point." (PMID 25329832, 2014). "Accordingly, ex vivo-generated DC or tumor cells co-expressing transgene IL-15 and IL-15Rα, and engineered IL-15 agonists (e.g., IL-15/IL-15Rα-Fc complex, IL-15/IL-15Rα fusion protein) have been explored to generate effective antitumor responses." (PMID 25941586, 2014). "Previous studies have done depletion of NK cells prior to treatment to show that NK cells contribute to the anti-tumor effect of IL15/IL15Rα." (PMID 25329832, 2014).